ALK (ALK receptor tyrosine kinase)
Diseases named in the same sentence as ALK in open-access papers (continued):
Sharing a sentence is not in itself a finding about the gene and the disease.
neuroblastoma (continued). "Full-length ALK is expressed in neuroblastoma, and is a fairly frequent target of genetic alterations leading to activating mutations in cases of both familial (1–2%) and sporadic (6–10%) primary neuroblastoma." (PMID 37414143, 2023). "The gene encoding the RTK ALK (anaplastic lymphoma kinase) was identified as a neuroblastoma predisposition gene, and constitutive active mutations are found in both germline and somatically acquired neuroblastomas and in ∼20%–43% of relapsed neuroblastoma patients." (PMID 37877351, 2023). "There was limited evidence that ALK mutation, the most frequently mutated gene in neuroblastoma, may be associated with Cluster-1, although this was of borderline significance." (PMID 36175618, 2022). "However, few were recurrent, with only ALK variants R127Q, R1275Q, F1174C and F1174L previously reported in neuroblastoma." (PMID 35768791, 2022). "Prior to screening, we investigated ALK inhibitor responses of ALK-mutated neuroblastoma cell lines harboring MYCN amplifications (KellyALKF1174L, LAN-5ALKR1275Q) or non-amplified MYCN (SH-SY5YALKF1174L) to select a cell line and establish suitable ALKi concentrations for screening." (PMID 35689207, 2022). "It had the effect of synergistic anti-BRAF (v-raf murine sarcoma viral oncogene homolog B1) mutation melanoma cell proliferation with RAF kinase inhibitor, and synergistic anti-ALK (anaplastic lymphoma kinase) mutation neuroblastoma with ALK inhibitor and prolonged survival." (PMID 35831864, 2022). "The role of ALK as a driver mutation in neuroblastoma leads to the hypothesis that loss of an ALK mutation at relapse is very rare." (PMID 36029175, 2022). "Further, the ALK gene is frequently mutated in both familial and sporadic neuroblastoma." (PMID 36140661, 2022). "Together, the high somatic mutation frequencies and associations with other variants suggested a prominent role for mutations of chromosome 1 genes in the clinical spectrum of neuroblastoma, in addition to those of more established gene candidates like ALK and ATRX." (PMID 35768791, 2022). "In 2004, PHOX2B (paired-like homeobox 2b) was the first to be identified as a neuroblastoma predisposition gene, and in 2008, the ALK (anaplastic lymphoma kinase) gene was reported as the major cause of hereditary neuroblastoma, and shown to also be frequently mutated in sporadic neuroblastoma." (PMID 36140661, 2022). "SNP-microarray analysis in combination with WGS indicates relatively quiet genomes with very low mutational burden, suggesting that oncogenic ALK may be sufficient for early neuroblastoma development." (PMID 36140661, 2022). "In addition, anti ALK antibodies have also been found to specifically inhibit neuroblastoma growth in ALK mutated human neuroblastoma derived cell lines." (PMID 36591504, 2022). "In addition, tumor and liquid biopsy samples of four patients with ALK-mutated neuroblastomas before ALK inhibitor treatment and during tumor progression under treatment were genomically profiled." (PMID 35689207, 2022). "We recurrently detected NF1 loss-of-function mutations as well as activating mutations in RAS and its analogues in clinical samples from ALK inhibitor-resistant neuroblastomas and confirmed the causal contribution of these mutations to ALK inhibitor resistance in preclinical models." (PMID 35689207, 2022). "Mutations of ALK pose a high susceptibility to neuroblastoma." (PMID 34020009, 2021). "Moreover, LTK is expressed in human leukaemia cells and activating mutations (mimicking ALK neuroblastoma-related mutations) were able to induce transformation in haematopoietic cells." (PMID 34020009, 2021). "Interestingly, inhibition of STAT3 leads to decreased growth and viability of neuroblastoma cell lines, in addition to decreased levels of MYCN in neuroblastoma cell lines carrying ALK mutations." (PMID 34769149, 2021). "A more common lesion associated with familial neuroblastoma is found in the ALK locus." (PMID 34796286, 2021).
neuroblastoma (continued). "CCC-003 exhibited high cytotoxicity in ALK-mutated neuroblastoma cells." (PMID 34591871, 2021). "Most of these mutations are located in the tyrosine kinase domain and lead to constitutive phosphorylation, indicating that ALK mutations found in neuroblastoma may be oncogenic drivers." (PMID 34796286, 2021). "The inhibition of these factors in combination with ALK inhibition could provide a new strategy for treatment of high‐risk neuroblastoma." (PMID 33932101, 2021). "This strategy is being pursued in an ongoing phase III trial for newly-diagnosed high-risk neuroblastoma patients with amplification or mutation of ALK who will receive crizotinib in combination with all planned adjuvant therapy (ClinicalTrials.gov Identifier: NCT03126916)." (PMID 34298746, 2021). "Gain-of-function mutations in ALK are the predominant driver of familial neuroblastoma." (PMID 34769149, 2021). "Although the preclinical data suggested that ALK mutations in neuroblastoma cells could be sensitive to ALK inhibition, additional studies with crizotinib are required to present clear evidence." (PMID 34769519, 2021). "Finally, NOTCH1 mutations in NSCLC and ALCL, and PIM1 overexpression in neuroblastoma, also cause ALK TKI resistance through their effects on the JAK-STAT pathway." (PMID 34885113, 2021). "ALK F1174L mutation is a major aberration observed in both primary and relapsed neuroblastomas." (PMID 34591871, 2021). "Activating mutations of anaplastic lymphoma kinase (ALK) or amplifications of the ALK gene, found in >10–15% of high-risk neuroblastomas, are correlated with adverse outcomes, but also define a potential target for a molecular-targeted therapy with ALK inhibitors." (PMID 34442335, 2021). "In addition to HCC, ALK overexpression or phosphorylation is linked to unfavorable course of disease also in inflammatory breast cancer as well as neuroblastoma, where ALK phosphorylation is linked to activating mutations of the ALK gene." (PMID 34029351, 2021). "As an example, neuroblastoma cell lines with ALK variants or ALK amplification in athymic nude and SCID mice have been used to study ALK inhibitors alone, and in combination with chemotherapy, demonstrating improved tumor control and prolonged survival in these models." (PMID 33659929, 2021). "To clarify whether CCC-003 induces cell death in ALK-mutated neuroblastoma cells, we performed Annexin V staining." (PMID 34591871, 2021). "CCC-003 suppressed cell proliferation in ALK-mutated neuroblastoma cells." (PMID 34591871, 2021). "Despite the well-established prognostic significance of ALK mutations in neuroblastoma, a phase I/II clinical trial for pediatric patients with relapsed and refractory solid tumors yielded complete responses in only 1 out of 11 patients with known ALK mutations (NCT00939770)." (PMID 34722256, 2021). "Additionally, other important genetic markers for neuroblastoma are mutations in ALK, PTPN11, TERT, ATRX, and amplification of MYCN." (PMID 34885007, 2021). "Our present multi-region sequencing study of 10 patients with neuroblastoma shows extensive spatial and temporal intratumour heterogeneity that also affected genes encoding actionable targets, such as ALK and FGFR1, thus, harbouring potential implications for therapeutic target selection." (PMID 34815394, 2021). "Interestingly, we found the hotspot mutation F1174L in ALK, frequently observed in neuroblastoma tumors." (PMID 33381456, 2020). "Therefore, the fly eye has become a valuable model system to analyze putative activating human ALK mutations identified in neuroblastoma patients." (PMID 32917927, 2020). "In neuroblastoma, flotillin 1 was identified from a screen as a phosphotyrosine-containing protein associated with the oncogenic anaplastic lymphoma kinase (ALK) and was shown to control ALK activity through its stabilization at the plasma membrane." (PMID 32297092, 2020).
neuroblastoma (continued). "Furthermore, activating ALK mutations have also been reported to be enriched in relapsed neuroblastoma together with other mutations driving RAS/MAPK signalling." (PMID 31937834, 2020). "Further, in human neuroblastoma-derived cell lines with either WT or mutated ALK (F1174L, R1275Q), antagonistic antibody against ALK’s extracellular domain resulted in specific inhibition of neuroblastoma cell growth with antibody-dependent cellular toxicity in vitro." (PMID 32059449, 2020). "Identification of somatic mutations, fusions, and other genomic aberrations has led to implementation of molecularly targeted therapies in several pediatric cancers, including Philadelphia chromosome positive (Ph (+)) and Ph-like acute lymphoblastic leukemia and ALK-mutated neuroblastoma." (PMID 31133068, 2019). "Since repotrectinib shows selectivity for ALK, we decided to investigate repotrectinib in a neuroblastoma setting focusing on its effects on ALK, including ALK gain of function mutations relevant in neuroblastoma." (PMID 31852910, 2019). "ALK encodes a tyrosine kinase receptor linked to neuroblastoma." (PMID 29858598, 2019). "Thus, alectinib exhibits strong activity toward many of the ALK neuroblastoma mutant variants with the exception of the ALK-I1171 mutations which are more resistant." (PMID 31334113, 2019). "The ALK gene is a major oncogene of neuroblastoma cases exhibiting ALK activating mutations." (PMID 31452835, 2019). "The most commonly found ALK mutations in neuroblastoma are ALK-F1174L, ALK-F1245C, and ALK-R1275Q." (PMID 31334113, 2019). "More than 35 different mutations in ALK have been reported in neuroblastoma." (PMID 30760980, 2019). "Importantly, the three “hot spot” mutations found in neuroblastoma patients (ALK-F1174L, ALK-F1245C and ALK R1275Q) display low IC50 values for the inhibition of ALK phosphorylation with repotrectinib." (PMID 31852910, 2019). "Importantly, small molecules for targeted therapy of ALK have been developed and neuroblastoma cell lines harboring p.R1275 mutations show sensitivity towards ALK inhibitors, such as crizotinib." (PMID 31466397, 2019). "Although many molecular prognostic factors have been described in neuroblastoma only activating ALK mutations and MYCN overexpression have been proven to be de novo oncogenic drivers as mutation or overexpression of these molecules give rise to neuroblastoma in genetically engineered mouse models." (PMID 30760980, 2019). "Initial efforts determined that the majority of these cases are associated with activating germline mutations in the anaplastic lymphoma kinase (ALK) gene, and subsequent studies identified ALK gene mutations or gene amplifications in up to 15% of sporadic high-risk neuroblastoma tumors." (PMID 30384486, 2018). "Concurrently, mutations in ALK were also reported in 10–12% of sporadic cases of neuroblastoma." (PMID 30200332, 2018). "ALK mutations are also implicated in the majority of familial neuroblastoma cases." (PMID 30326621, 2018). "The COG is now conducting a phase 3 clinical trial to determine whether the addition of crizotinib to standard of care therapy for high risk neuroblastoma improves survival for patients whose tumor harbors an ALK aberration (NCT03126916)." (PMID 30326621, 2018). "Several recurrently mutated genes or loci which correlated with high-risk neuroblastoma have been identified, such as ALK mutations or amplifications, PHOX2B mutation, chromosome 1p and 11q deletions, truncating or structural variants of ATRX gene, genomic rearrangements of TERT." (PMID 30405689, 2018).
neuroblastoma (continued). "In addition to ALK-activated point mutations, truncated activated ALK mutants, including ALK Δ2–3, ALK Δ1–5, and ALK Δ4–11, have been found in several neuroblastoma-derived cell lines and tumor samples." (PMID 30400214, 2018). "A number of other tumours of which there is limited experience at present include thyroid-like follicular RCCs, RCCs with angioleiomyomatous stroma, the oncocytic RCC that occurs post-neuroblastoma treatment and RCCs exhibiting ALK gene rearrangements, monosomy 8 and TCEB1 mutations." (PMID 30123932, 2018). "However, relapsed neuroblastomas contain higher numbers of recurrent and targetable mutations such as those in ALK." (PMID 28924803, 2018). "Furthermore, targetable mutations, possibly driving tumor progression and/or treatment resistance, can be found in subpopulations of aggressive tumors, e.g., ALK mutations in neuroblastoma." (PMID 28924803, 2018). "These experiments identified the neuroblastoma predisposition gene ALK as a candidate gene." (PMID 29515255, 2018). "In conclusion, while mutations in full length ALK leading to activation of the receptor are well characterised in neuroblastoma and supported by a substantial body of work, the activation of full length ALK in thyroid cancer requires further critical evaluation." (PMID 28030793, 2017). "Gain‐of‐function mutations of ALK, which lead to constitutive ALK phosphorylation, are known to contribute to the aggressive nature of pediatric neuroblastoma tumors, and therefore, the detection of ALK activity in available neuroblastoma cell lines is of increasing importance." (PMID 28432815, 2017). "However, there are still limitations likely associated with treating ALK-aberrant neuroblastoma with single-agent ALK inhibitors, including the newer generation inhibitors." (PMID 28425916, 2017). "In addition, ALK mutations have been identified in both low- and high-risk neuroblastoma with equal frequency, suggesting that activated ALK cooperates with other oncogenic aberrations to define high- versus low-risk tumors." (PMID 28425916, 2017). "However, the recurrent somatic mutations of the tyrosine kinase receptor ALK identified in 8-10% of primary neuroblastoma tumours and the emergence of ALK mutations at relapse mark ALK as an important novel drug target." (PMID 29290991, 2017). "Familial neuroblastoma is largely explained by germline mutations in ALK or PHOX2B." (PMID 28545128, 2017). "Here, we describe the experimental analysis of ALK-Y1278S, a mutation in the activation loop of the ALK kinase domain, observed in at least four neuroblastoma patients that harbours both in vitro and in vivo gain of funtion activity, which is in agreement with recently reported observations." (PMID 29084134, 2017). "Besides amplification of the MYCN oncogene (in approximately 20% of neuroblastomas), ALK mutations and amplifications occur in 9% and 2-3%, respectively." (PMID 29221117, 2017). "The p.R1275Q ALK mutation observed in one of our thymic carcinomas is an activating point mutation in the kinase domain and known as one of the most common mutations in neuroblastoma." (PMID 27844328, 2017). "ALK amplification is strongly associated with high-risk neuroblastoma and an inferior outcome, and multivariate analysis suggested an independent influence on survival for both ALK gain and amplification in a cohort of 1596 neuroblastoma samples enrolled in a COG biology study." (PMID 29156716, 2017). "MYCN amplifications and activating ALK mutations or amplifications define, among other molecular aberrations, patient subgroups with highly aggressive and frequently therapy-resistant neuroblastomas." (PMID 29156716, 2017). "It has single-agent antitumor activity in neuroblastoma xenografts that express the three most common ALK mutations – F1174L, R1275Q and F1245C, providing the rationale to test more potent ALK inhibitors in clinic." (PMID 28425916, 2017).
neuroblastoma (continued). "In addition, ceritinib and CGM097 combination overcomes acquired ceritinib resistance caused by MYCN upregulation in an ALK-driven neuroblastoma model." (PMID 28425916, 2017). "Several inhibitors of the tyrosine kinase ALK have been evaluated in clinical studies for adult cancer patients, and the inherent resistance of the ALK mutations found in pediatric neuroblastomas necessitates thorough preclinical investigation of the available compounds." (PMID 28432815, 2017). "Interestingly, by analyzing a neuroblastoma cell line panel, we found that cells with the ALK R1275Q mutation had the strongest ALK phosphorylation signals." (PMID 28432815, 2017). "The potential interaction of each of these molecules in RET signaling (except for ALK), indicates that this “pair” may be a linked activation complex in neuroblastoma." (PMID 28871274, 2017). "Employing neuroblastoma cell lines, mouse xenograft and Drosophila melanogaster model systems expressing different constitutively active ALK variants, we show clear and efficient inhibition of ALK activity by brigatinib." (PMID 27049722, 2016). "Taken together, our data suggest that PF-06463922 may be a superior treatment for ALK-positive neuroblastoma, defined by the presence of kinase-activating point mutations." (PMID 27483357, 2016). "Activating ALK mutations are reported in both hereditary and sporadic neuroblastoma tumours, and several ALK inhibitors are currently under clinical evaluation as novel treatments for neuroblastoma." (PMID 27888620, 2016). "Therefore, amplification of MYCN can also involve ALK amplification, and neuroblastoma patients bearing both MYCN amplification and ALK mutations are characterized by an unfavorable aggressive neuroblastoma phenotype." (PMID 27049722, 2016). "NRAS und ALK mutations in selected neuroblastoma cell lines." (PMID 26821351, 2016). "Given that mutated ALK shares the same ATP pocket with fusion ALK proteins, neuroblastoma patients with aberrant ALK fusion proteins could benefit from Crizotinib treatment." (PMID 27732954, 2016). "We assembled a panel of neuroblastoma cell lines harboring mutated or wild-type ALK as follows: CLB-GE (amplified MYCN/ALK, ALKF1174V), CLB-BAR (amplified MYCN/ALK, ALK Δexon 4-11), IMR32 (ALK exon 2-4 amplified ALK), CLB-PE (amplified MYCN) and SK-N-AS (non-amplified MYCN, WT ALK)." (PMID 27483357, 2016). "However, in neuroblastoma, activating mutations in the ALK kinase domain are typically refractory to crizotinib treatment, highlighting the need for more potent inhibitors." (PMID 27483357, 2016). "The increased affinity of PF-06463922 for EML4-ALKL1196M suggests that this ALK inhibitor may be more effective against the ALK activating mutations described in neuroblastoma." (PMID 27483357, 2016). "Thus, brigatinib shows inhibition of multiple gain-of-function ALK neuroblastoma mutations including the “hot-spot” mutations as well as the crizotinib resistant ALK-G1269A mutation." (PMID 27049722, 2016). "Neuroblastoma is a complex heterogeneous disease exhibiting a variety of characteristic patterns of genetic aberrations that correlate with clinical outcome, of which cases with ALK mutation and MYCN amplification are more aggressive in nature." (PMID 27483357, 2016). "In addition, the tyrosine kinase receptor ALK, the most frequently mutated gene in familial neuroblastoma, somatically acquired amplification of MYCN and hemizygous deletions of chromosomes 1p and 11q are highly recurrent and associated with poor prognosis." (PMID 27351283, 2016). "In addition, in neuroblastoma, subclonal ALK mutations can be present at diagnosis with subsequent clonal expansion at relapse." (PMID 27483357, 2016). "Few recurrent genetic events have been linked to neuroblastoma including tumour-specific amplification of the MYCN oncogene or mutations in the genes coding for anaplastic-lymphoma kinase (ALK) and the alpha thalassemia/mental retardation syndrome X-linked (ATRX) gene." (PMID 27716771, 2016).